ALKBH4 (alkB homolog 4, lysine demethylase)
Diseases named in the same sentence as ALKBH4 in open-access papers:
ALKBH4 is named in the same sentence as 17 diseases in open-access papers, as found by Europe PMC text mining. Sharing a sentence is not in itself a finding about the gene and the disease. The quoted sentences say what the papers report.
colorectal cancer (3 papers, 2020 to 2024). A primary or metastatic malignant neoplasm that affects the colon or rectum. "Previous data have shown that ALKBH4 functions to suppress colorectal cancer metastasis through competitive binding to WDR5." (PMID 37207134, 2022). "In contrast, in colorectal cancer (CRC), ALKBH4 acts as a tumor suppressor, inhibiting the invasive and metastatic ability of CRC cells by inhibiting epithelial-mesenchymal transition (EMT)." (PMID 38902235, 2024).
non-small cell lung carcinoma (3 papers, 2021 to 2024). A group of at least three distinct histological types of lung cancer, including non-small cell squamous cell carcinoma, adenocarcinoma, and large cell carcinoma. "Conversely, ALKBH4 promotes tumorigenesis in non-small-cell lung cancer and correlates with poor prognosis." (PMID 37207134, 2022). "It has been reported that ALKBH4 is overexpressed in head and neck squamous cell carcinoma (HNSCC) and non-small-cell lung cancer (NSCLC)." (PMID 38902235, 2024).
breast carcinoma (2 papers, 2021 to 2022). "We showed that ALKBH4 knockdown induced the downregulation of cell proliferation and G1 arrest in breast cancer cell line MCF-7 cells, as well as in NSCLC cells (respectively)." (PMID 33883577, 2021). "It is short of direct proof about the relationship between ALKBH family and stage or subclasses in breast cancer, this study provided that ALKBH1, ALKBH4, and ALKBH6 might be associated with later stage, while ALKBH8 was relative to an earlier stage." (PMID 35980268, 2022). "As the data shown, the OS of breast cancer patient was significant difference when gene expression was changed in ALKBH3 (p=0.00063), ALKBH4 (p=0.013), ALKBH7 (p=0.0025), ALKBH8 (p=0.00013) and FTO (p=0.045)." (PMID 35980268, 2022). "With compared the expression of ALKBH family members in breast cancer and normal samples, the up-regulation was ALKBH1, ALKBH2, ALKBH4, ALKBH6, ALKBH7, and others such as ALKBH3, ALKBH8, FTO was down-regulation." (PMID 35980268, 2022).
lung adenocarcinoma (2 papers, 2021 to 2024). A carcinoma that arises from the lung and is characterized by the presence of malignant glandular epithelial cells. "A higher proportion of ALKBH4-expressing cancer cells was observed in lung adenocarcinoma than other histological types." (PMID 38369589, 2024).
gastric adenocarcinoma (1 paper, 2024). "The ROC curve analysis of ALKBH4 in gastric adenocarcinoma demonstrated an AUC of 0.777 (95% CI: 0.711–0.843), indicating a moderate predictive performance." (PMID 38902235, 2024).
gastric cancer (1 paper, 2024). A primary or metastatic malignant neoplasm involving the stomach. "Downregulating the expression of ALKBH4 markedly enhanced the susceptibility of gastric cancer cells to 5-FU, leading to the suppression of gastric cancer cell proliferation." (PMID 38902235, 2024). "To elucidate the underlying mechanism of how ALKBH4 inhibits pyroptosis in gastric cancer cells, we evaluated the impact of ALKBH4 expression on key targets (GSDME, GSDMD, NLRP3, Caspase 1) of the pyroptosis pathway using qPCR and western blot experiments." (PMID 38902235, 2024). "The inhibitory effect of 5-FU treatment alone on gastric cancer was higher than the inhibitory effect of gastric cancer by knocking down ALKBH4." (PMID 38902235, 2024). "Quantitative analysis revealed a higher incidence of pyroptosis markers in gastric cancer cells following ALKBH4 knockdown compared to the control group." (PMID 38902235, 2024). "Conversely, GSDME knockdown negated the gastric cancer growth inhibitory effect induced by ALKBH4 downregulation and 5-FU treatment." (PMID 38902235, 2024). "Taken together, our study demonstrates the potential value of ALKBH4 as a novel therapeutic target for improving chemosensitivity by regulating the pyroptosis process of gastric cancer cells." (PMID 38902235, 2024). "It was found that the expression of ALKBH4 in gastric cancer tissues was significantly higher than that in adjacent normal tissues." (PMID 38902235, 2024). "The overexpression of ALKBH4 was found to enhance the proliferation activity of gastric cancer cells, while the knockdown of ALKBH4 was observed to inhibit the proliferation activity of gastric cancer cells." (PMID 38902235, 2024). "And our findings show that elevated ALKBH4 expression can effectively enhance the proliferation and advancement of gastric cancer both in vitro and in vivo." (PMID 38902235, 2024). "In our study, we found high expression of ALKBH4 in gastric cancer and its positive correlation with poor prognosis of GC patients through the TCGA database." (PMID 38902235, 2024). "In summary, our results confirm that ALKBH4 attenuates the sensitivity of gastric cancer cells to 5-FU treatment by inhibiting GSDME transcription." (PMID 38902235, 2024). "The mechanism of action of ALKBH4 in gastric cancer involves reducing the level of H3K4me3 modification in the promoter region of GSDME by acting as a demethylase, leading to the inhibition of GSDME transcriptional activation." (PMID 38902235, 2024). "ΔIRS (Immunohistochemical reaction score) of ALKBH4 staining also confirmed that ALKBH4 was highly expressed in gastric cancer tissues." (PMID 38902235, 2024). "Through qPCR experiments, we observed significant upregulation of ALKBH4 at mRNA levels in gastric cancer tumors." (PMID 38902235, 2024). "In this study, we observed a significant upregulation of ALKBH4 expression in gastric cancer tissues compared to adjacent normal tissues, indicating its potential as a predictor for the poor prognosis of gastric cancer patients." (PMID 38902235, 2024). "Conversely, knockdown of ALKBH4 expression can significantly inhibit the proliferation of gastric cancer cells." (PMID 38902235, 2024). "The combination of 5-FU and ALKBH4 knockdown demonstrated the most efficacious therapeutic outcome in this experiment, with a notable reduction in gastric cancer proliferation and progression." (PMID 38902235, 2024). "In our subsequent research, we observed a significant upregulation of demethylase ALKBH4 in gastric cancer." (PMID 38902235, 2024). "Our animal experiments results have been consistent with the results of in vitro cellular experiments, suggesting that ALKBH4 acts as a tumor-promoting factor in mice, and knockdown of ALKBH4 significantly inhibited the proliferative capacity of gastric cancer cells." (PMID 38902235, 2024). "In addition, knockdown of ALKBH4 aggravated the inhibitory effect of 5-FU on the proliferation of gastric cancer cells." (PMID 38902235, 2024).
gastric cancer (continued). "Nevertheless, the impact of altered ALKBH4 expression in gastric cancer cells on disease progression and chemotherapy sensitivity remains unclear." (PMID 38902235, 2024). "Our findings indicate that the inhibition of ALKBH4 expression may enhance the sensitivity of gastric cancer cells to 5-FU by increasing the expression level of GSDME in gastric cancer." (PMID 38902235, 2024). "The knockdown of ALKBH4 inhibited the proliferation and retarded the growth of gastric cancer." (PMID 38902235, 2024). "The role of FTO in the progression of gastric cancer has been widely investigated; however, the role of ALKBH4 remains unclear." (PMID 38902235, 2024). "Kaplan–Meier survival analysis showed that high expression of ALKBH4 may lead to shorter overall survival, first prognostic survival, and post-progression survival in patients with gastric cancer." (PMID 38902235, 2024). "Moreover, we administered dimethyl fumarate (DMF), a pyroptosis inhibitor for GSDME/GSDMD, to the cells and noted a reduction in cell mortality, indicating that ALKBH4 mediates the sensitivity of gastric cancer cells to 5-FU through GSDME." (PMID 38902235, 2024). "In addition, we also found that high expression of ALKBH4 can inhibit pyroptosis and promote the proliferation of gastric cancer cells." (PMID 38902235, 2024). "Furthermore, we have identified the pivotal role played by ALKBH4 in increasing the response of gastric cancer cells towards 5-FU chemotherapy." (PMID 38902235, 2024). "Moreover, gastric cancer patients with high ALKBH4 expression exhibited a poor overall survival rate." (PMID 38902235, 2024). "Furthermore, ALKBH4 expression was higher in gastric cancer cell lines MKN45, HGC-27, and AGS compared to fibroblasts." (PMID 38902235, 2024). "Furthermore, we verified that ALKBH4 was significantly overexpressed in gastric cancer tissues by TNM plot online database." (PMID 38902235, 2024). "The results of immunohistochemistry experiments demonstrated that the proportion of GSDME staining increased and Ki67 staining decreased in xenograft tumors following ALKBH4 knockdown, thereby providing further evidence that ALKBH4 knockdown inhibits gastric cancer proliferation." (PMID 38902235, 2024). "However, ALKBH8 was highly expressed in only six pairs of gastric cancer tissues, while ALKBH4 was highly expressed in seven pairs, and FTO was highly expressed in all 10 pairs." (PMID 38902235, 2024). "Furthermore, we performed Gene Set Enrichment Analysis (GSEA) and confirmed that ALKBH4 amplification was indeed positively correlated with chromatin assembly and depolymerization in gastric cancer." (PMID 38902235, 2024). "Although studies have confirmed that ALKBH4 is involved in the negative regulation of GSDME expression in gastric cancer cells, there are still many unknowns in other related pathways that ALKBH4 regulates pyroptosis." (PMID 38902235, 2024). "We found that in 10 pairs of human gastric cancer and normal tissues, ALKBH1, ALKBH4, ALKBH8, and FTO were highly expressed in the gastric cancer tissues." (PMID 38902235, 2024). "To investigate the specific mechanism of ALKBH4’s effect on 5-FU chemosensitivity in gastric cancer cells, we conducted TUNEL and PI immunofluorescence experiments and found that knockdown of ALKBH4 promoted 5-FU-induced cell death." (PMID 38902235, 2024). "Subsequent plate cloning experiments showed that the cell proliferation ability of MKN45 and HGC-27 GC cells was significantly inhibited after 5-FU treatment, and the overexpression of ALKBH4 rescued the inhibitory effect of 5-FU on the proliferation of gastric cancer cells." (PMID 38902235, 2024). "Mechanistically, ALKBH4 inhibits GSDME activation at the transcriptional level by inhibiting H3K4me3 histone modification in the GSDME promoter region, thereby reducing the sensitivity of gastric cancer cells to 5-FU treatment." (PMID 38902235, 2024).
gastric cancer (continued). "The Western blot analysis demonstrated that ALKBH4 protein expression was notably higher in gastric cancer cell lines (AGS, MGC803, HGC-27, and MKN45) compared to normal mucosal epithelial cells (GES-1)." (PMID 38902235, 2024). "In this study, we found that ALKBH4 inhibited the expression of GSDME in gastric cancer, thereby reducing 5-FU-induced pyroptosis, eventually leading to reduced sensitivity of gastric cancer cells to 5-FU treatment and promoting gastric cancer progression." (PMID 38902235, 2024). "After knocking down ALKBH4, we found that the IC50 values of both cells were decreased, suggesting that the decreased expression of ALKBH4 may promote the sensitivity of gastric cancer cells to 5-FU." (PMID 38902235, 2024). "Importantly, we demonstrate that ALKBH4 knockdown amplifies GSDME transcriptional activation, thereby facilitating chemotherapeutic drug-induced pyroptosis and ultimately enhancing the chemosensitivity of gastric cancer cells." (PMID 38902235, 2024). "However, ALKBH4 regulates gastric cancer progression through demethylation has not been reported." (PMID 38902235, 2024).
pancreatic cancer (1 paper, 2021). "To examine whether ALKBH4 specifically promotes cell proliferation in NSCLC cells or not, first, we examined the expression of ALKBH4 in some cancer cell lines (prostate, liver, lung, breast, renal, and pancreatic cancer cell lines)." (PMID 33883577, 2021).
squamous cell carcinoma (1 paper, 2021). A carcinoma arising from squamous epithelial cells. "To investigate the function of ALKBH4 in NSCLC cells, we first evaluated the expression of ALKBH4 in 22 NSCLC cell lines (adenocarcinoma: 15 cell lines; squamous cell carcinoma: 7 cell lines)." (PMID 33883577, 2021).
tumor (6 papers, 2020 to 2024). "ALKBH4 has been previously illustrated in mediating demethylation of a monomethylated site in actin and depletion of ALKBH4 contributes to defects in cytokinesis and cell motility, however, the underlying molecular mechanisms of ALKBH4 in tumor remain unknown." (PMID 32478065, 2020). "Therefore, although the underlying mechanism should be analysed, the tumour promoting role of ALKBH4 in NSCLC might partly rely on WDR5." (PMID 33883577, 2021). "Depletion of ALKBH4 significantly impedes NSCLC cell proliferation by inducing G1 phase cell cycle arrest during tumor growth in vivo." (PMID 38902235, 2024). "Densitometry analysis confirmed a statistically significant upregulation of ALKBH4 in tumor cells when compared to normal cells (p < 0.05)." (PMID 38902235, 2024). "Lysine demethylase ALKBH4 has been shown to be upregulated in a variety of tumors to promote tumor progression." (PMID 38902235, 2024). "Through the TIMER online website and the XIANTAO tool, we analyzed the mRNA expression levels of ALKBH4 in various tumor types in TCGA and GTEx databases." (PMID 38902235, 2024). "Taken together, these results illustrate that ALKBH4, acting as a DNA 6mA demethylase, is critical for arsenic-induced skin tumorigenesis." (PMID 37207134, 2022). "Overall, these results clearly demonstrate that ALKBH4 is required for arsenic-induced malignant transformation and tumorigenicity and suggest that ALKBH4 is a tumor-promoting enzyme involved in arsenic-induced tumorigenesis." (PMID 37207134, 2022). "ALKBH4 knockdown significantly induced the downregulation of NSCLC cell proliferation via cell cycle arrest at the G1 phase of in vivo tumour growth." (PMID 33883577, 2021). "Compared to adjacent normal lung tissues, ALKBH4 expression was significantly higher in tumour tissues." (PMID 33883577, 2021). "In cultured CRC cells and mouse tumor metastasis models, overexpression of ALKBH4 markedly inhibits cell migration in vitro and metastasis in vivo." (PMID 32478065, 2020). "In vitro transwell assay and in vivo metastatic tumor model were performed to explore the biological function of ALKBH4 in the metastasis of CRC." (PMID 32478065, 2020). "Furthermore, in vivo, we found that As-Tr cells with ALKBH4 knockdown displayed drastically reduced tumor growth and weight when injected into nude mice." (PMID 37207134, 2022). "Moreover, patients with high ALKBH4 expression showed a poor prognosis, suggesting that ALKBH4 plays a pivotal tumour-promoting role in NSCLC." (PMID 33883577, 2021). "We found that ALKBH4 functions as a tumour promoter in NSCLC." (PMID 33883577, 2021). "Additionally, we demonstrate the tumour-promoting role of ALKBH4 via its enzymatic activity in NSCLC cells." (PMID 33883577, 2021). "Furthermore, overexpression of ALKBH4 dramatically reduced lung metastasis in metastatic tumor model." (PMID 32478065, 2020). "Furthermore, the ALKBH4 might show the tumor-promoting effect and negatively affect the prognosis of patients with HCC." (PMID 34557360, 2021). "In the present study, we demonstrated that ALKBH4 is highly expressed in cell lines as well as in tumour tissues of NSCLC patients, and that it functions as a tumour promoter via its enzymatic activity." (PMID 33883577, 2021). "On account of the advance stage which indicates progression, ALKBH1, ALKBH4, ALKBH6, and ALKBH8 may be the potential biomarker for predicting tumor progression." (PMID 35980268, 2022). "The immunohistochemical analysis showed that ALKBH4 was positive in 35 tumours and negative in 45 tumours." (PMID 33883577, 2021). "Analysis of the primary tumor tissue showed that patients with distant metastasis exhibited lower mRNA expression of ALKBH4 than those without metastasis both in Renji Cohort1 and microarray dataset (GSE21510) from GEO database." (PMID 32478065, 2020).
tumor (continued). "Interestingly, a higher ALKBH4 expression was detected in tumour tissues than in matched-pair normal tissues, regardless of the presence or absence of epidermal growth factor receptor (EGFR) gene mutations." (PMID 33883577, 2021). "Moreover, the enzymatic domain of ALKBH4 was critical for the upregulation of cell proliferation in NSCLC cells, suggesting that ALKBH4 may function as a tumour promoter by targeting N6-adenosine modification in NSCLC cells." (PMID 33883577, 2021). "Since ALKBH4 knockdown downregulated the expression of PLK1 and PLK4, ALKBH4 may function as a tumour promoter by accelerating cancer cell proliferation via upregulation of E2F1 signalling in early stage, and by promoting metastasis via upregulation of PLK signalling in late-stage NSCLC." (PMID 33883577, 2021).
cancer (5 papers, 2020 to 2024). A tumor composed of atypical neoplastic, often pleomorphic cells that invade other tissues. "It suggests that ALKBH4 affects the development of cancer cells in different cancers through different pathways." (PMID 37007161, 2023). "ALKBH4 was highly expressed in many of the cancer cell lines examined." (PMID 33883577, 2021). "However, the expression and function of the lysine demethylase ALKBH4 in cancer are poorly understood." (PMID 33883577, 2021). "However, the expression, substrate and biological function of ALKBH4 in other cancers are currently unknown." (PMID 33883577, 2021). "Moreover, an increased ALKBH4 expression was shown in broad types of cancer." (PMID 33883577, 2021). "Therefore, we propose that ALKBH4 may be an important molecular target for, not only NSCLC, but also for a wide range of cancers." (PMID 33883577, 2021).
ALKBH4 also shares sentences with these, for which no sentence is quoted: adenocarcinoma (1 paper); colon cancer (1); head and neck squamous cell carcinoma (1); lung carcinoma (1); lung squamous cell carcinoma (1); schizophrenia (1); skin cancer (1).